AR (androgen receptor)
Diseases named in the same sentence as AR in open-access papers (continued):
Sharing a sentence is not in itself a finding about the gene and the disease.
prostate carcinoma (continued). "There is a well-documented inverse relationship between AR and PI3K activity in prostate cancer; when AR is inhibited, it increases PI3K activity and vice-versa." (PMID 34926721, 2019). "AKT enhanced activity reduces AR dependence of prostate cancer cell; thus, it contributes to the development of castration resistant status." (PMID 30642011, 2019). "Migration of LNCaP cells (an AR-positive prostate cancer cell line) increased significantly when co-cultured with bone stromal cells isolated from prostate cancer bone metastases." (PMID 30871130, 2019). "After the discovery of the connection between AR gene expression and prostate cancer in the year 1995, this attracted Finnish researchers' interest." (PMID 30838019, 2019). "Treatment with JQ1 or I-BET762 is able to impair AR signaling and demonstrated pre-clinical efficacy in castration-resistant prostate carcinoma." (PMID 30841549, 2019). "To further substantiate these findings, we evaluated AR translocation in the human prostate cancer cell line PC346C, which naturally expresses ARwt and lacks CYP17A1 expression." (PMID 31017696, 2019). "Accordingly, it was shown that pre-adipocytes induce miR-301a expression in prostate cancer cells, leading to suppression of its target, AR, and subsequent activation of TGF-β/SMAD/MMP-9 signaling and promotion of cancer invasiveness in vivo." (PMID 31842336, 2019). "To address this prostate cancer mystery, we established an androgen-insensitive LNCaP cell subline, LNCaPdcc, to understand how the AR protein level is regulated in prostate cancer cells in an androgen-free environment." (PMID 31395805, 2019). "The expression of AR is an important regulator of prostate cancer cell growth and development at the early stage." (PMID 31137764, 2019). "For example, in prostate cancer, the androgen receptor is a primary target for current prostate cancer therapies." (PMID 31771198, 2019). "Androgen receptor (AR), a member of the NR superfamily, plays a key role in the onset and progression of prostate cancer, and numerous synthetic AR antagonists have been developed to inhibit the action of endogenous AR ligands (i.e. androgens)." (PMID 31501863, 2019). "Remarkably MEM suppressed AR/PSA signaling both in prostate cancer cell cultures and in the in vivo model." (PMID 31261861, 2019). "Having demonstrated heterogeneous AR output within prostate cancer cell lines, we asked if similar, intra-tumoral heterogeneity is observed clinically by immunohistochemical analysis of KLK3 and AR expression in several primary cancers." (PMID 30644358, 2019). "Ubiquitin-proteasome is involved in prostate cancer in various ways by modulating prostate cancer-related genes/proteins such as androgen receptor, heat shock protein (HSP) 90, cyclin-dependent kinase inhibitor p27, cyclin D1, and PTEN." (PMID 30972102, 2019). "Despite the key role played by androgen receptor (AR) in tumor cell aggressiveness and prostate cancer (PCa) progression, its function in the tumor microenvironment (TME) is still controversial." (PMID 31616657, 2019). "Our recent studies have elucidated several CCL-CCR axes involved in prostate cancer progression, some of which are negatively regulated by androgen/AR signaling and vice versa." (PMID 30871130, 2019). "This protein also plays an important role in driving the growth of prostate cancers, and doctors routinely treat such cancers with drugs that block the androgen receptor." (PMID 30644358, 2019). "In this study we used three different prostate cancer lines to establish role of FRG1 with respect to androgen receptor status and varying invasiveness." (PMID 30975102, 2019). "Androgen receptor (AR) signaling plays a key role not only in the initiation of prostate cancer (PCa) but also in its transition to aggressive and invasive castration-resistant prostate cancer (CRPC)." (PMID 31027362, 2019).
prostate carcinoma (continued). "Another curcumin derivative which has been used for prostate cancer treatment is dimethylcurcumin which improves AR degradation." (PMID 31801262, 2019). "This interpretation is supported by recently published in vitro data where treatment of two prostate cancer cell lines with either abiraterone or enzalutamide increased the expression of constitutively active AR-Vs (AR-V7 and AR-V567es)." (PMID 31289619, 2019). "In accordance with this, we previously reported genome-wide AR chromatin binding in prostate cancers and ERα profiles in endometrial cancers." (PMID 30620009, 2019). "Mechanistic studies in models of castration resistant, AR null prostate cancers demonstrate hyperactive MAPK signaling activated by paracrine and autocrine FGF/FGFR activation." (PMID 30804427, 2019). "Future investigations using AR rescue experiments are warranted to assess the role of 6-TG- and olaparib-mediated regulation of AR expression in the induction of apoptosis in castration-resistant prostate cancer cells." (PMID 31284411, 2019). "When AR function of C4-2 (a human prostate cancer cell line) cells were silenced with AR-siRNA (siAR), using scramble RNA (scr) as a control, siAR cells were observed to possess an increased migratory capacity." (PMID 30871130, 2019). "In human prostate cancer LNCaP cells, inhibition of Sp1 activity results in a strong decrease in the AR protein level, showcasing Sp1 relevance in the regulation of AR transcription." (PMID 31404977, 2019). "There is an urgent need for the development of novel targeted and immune therapies for this subtype of prostate cancer, when more deadly small-cell prostate cancers are induced by thorough androgen deprivation and androgen receptor ablation." (PMID 31552182, 2019). "There are several clinical trials in prostate cancer currently assessing the benefit of targeting the AR and PI3K/AKT pathways simultaneously." (PMID 34926721, 2019). "Hypoxia consequently enhances the transcriptional activity of AR in prostatic tumor cells at low androgen levels, such as seen in castration-resistant prostate cancer." (PMID 31151317, 2019). "This is a mechanism that involves the AR, not only in prostate cancer cells, but also in ovarian cells." (PMID 30717249, 2019). "This transcription factor has been shown to be involved in the proliferation of prostate cancer cells promoted by the Androgen Receptor (AR) and IRE1α." (PMID 31334233, 2019). "Recent acquisitions strongly indicate that reciprocal tumour-stroma interactions contribute to AR signalling in prostate cancer." (PMID 30832393, 2019). "Recent studies have demonstrated that ASC-J9® can suppress many AR-mediated diseases, including prostate cancer, liver cancer, and spinal and bulbar muscular atrophy neuron disease." (PMID 30894518, 2019). "The GREB1 promoter region has an androgen response element, GREB1 is induced by androgen in androgen receptor (AR)-positive prostate cancer cells." (PMID 31462641, 2019). "Androgen/AR signaling increases prostate cancer cell proliferation, while simultaneously inhibiting migration." (PMID 30871130, 2019). "TGF-β signaling in prostate cancer is regulated by a complex axis involving AR, miR-2909, and STAT1." (PMID 31842336, 2019). "Below we describe some common AR aberrations implicating this signaling node in prostate cancer pathogenesis." (PMID 31877956, 2019). "Since AR signaling is a major driver of prostate cancer growth, its targeting has been exploited for therapeutic benefit since past several decades." (PMID 31877956, 2019). "PSA, the downstream target gene of AR, is a representative biomarker for the progression of prostatic cancer and BPH." (PMID 31547405, 2019). "Many cell types, including prostate cancer, use AR to modulate specific gene expression, but prostate cancer cells uniquely require AR to regulate cell proliferation and cell survival." (PMID 31083651, 2019).
prostate carcinoma (continued). "Enzalutamide-resistant prostate cancer can also bypass androgen receptor blockade by glucocorticoid receptor activation." (PMID 31552182, 2019). "Androgen receptor (AR) plays important role in the development, progression, and metastasis of prostate cancer (PCa)." (PMID 31429764, 2019). "Particularly, they have explored the functional synergy in prostate cancers in mice resulting from the activation of the AR, KRAS, and AKT." (PMID 31366128, 2019). "More specifically, we evaluated an androgen receptor ChIP-seq dataset derived from prostate cancer cell line model LNCaP-1F5 and VCaP (Gene Expression Omnibus Series GSE39880, AR + DHT, RU486, or CPA)." (PMID 31084623, 2019). "As CK2 is elevated in PCa, and AR and NFκB are involved in the development and progression of prostate cancer, we investigated their interaction in benign and malignant prostate cells in the presence of altered CK2 expression." (PMID 31197122, 2019). "Resveratrol inhibited the expression of AR in prostate cancer cells and its activity was synergic with flutamide, an antagonist of AR." (PMID 30823649, 2019). "NEPC has been reported to be found in approximately 25% of patients with prostate cancer who received AR deprivation therapies." (PMID 30939845, 2019). "In advanced prostate cancer, when tumour cells can become resistant to antiandrogen treatment, they frequently grow via a hormone-independent, AR-driven process that remains incompletely understood." (PMID 31589603, 2019). "The ensemble of these data suggests that aberrations in AR and interacting proteins, including protein remodelers, ETS genes, and known AR coregulators are commonly mutated in prostate cancer." (PMID 31366128, 2019). "The aim of this study was to evaluate the effects of androgen stimulus and Tip60 overexpression on AR-dependent glycolytic alterations in prostate cancer." (PMID 31671779, 2019). "Most prostate cancers are androgen-sensitive malignancies whose growths depend on the transcriptional activity of the androgen receptor (AR)." (PMID 31552182, 2019). "AR transactivation induces the high expression of androgen-regulated genes, including transmembrane protease serine 2 (TMPRSS2) and long noncoding RNA prostate cancer-associated transcript 38 (PRCAT38)." (PMID 31405024, 2019). "Androgen receptor (AR) signaling, activated by androgen, plays an essential role in the initiation and progression of prostate cancer (PCa)." (PMID 31752909, 2019). "Although the function of AR signaling in BC is unclear, it is known to play important roles in prostate cancer occurrence and progression, and reportedly affects kidney, lung, breast and liver cancers." (PMID 30961575, 2019). "The main therapeutic strategy to treat prostate cancer patients for more than 4 decades has been ADT which targets AR and circulating male hormones." (PMID 31258834, 2019). "The majority of the prostate cancers (PCa) are adenocarcinomas characterized by glandular formation and the expression of androgen receptor (AR) and prostate-specific antigen (PSA)." (PMID 31694235, 2019). "A recent study revealed the enhancement of ubiquitination and the degradation of the androgen receptor (AR) in prostate cancer as a result of inhibiting USP14." (PMID 31013812, 2019). "One of the most important objectives of recent molecular studies has been to identify synergistic factors which, together with AR, are involved in prostate cancer progression." (PMID 31689899, 2019). "Our previous study supports this notion and defined a feed forward loop consisting of TMPRSS2-ERG fusions, androgen biosynthetic enzymes and AR activation operating in prostate cancer cells which drives intracellular DHT production." (PMID 31638934, 2019). "Our data confirmed the phenotype that kaempferol inhibited cell growth of AR-positive prostate cancer cell lines, LNCaP." (PMID 31871879, 2019).
prostate carcinoma (continued). "Our previous studies showed that UXT regulates transcription repression including androgen receptor (AR) signaling in prostate cancer." (PMID 30774773, 2019). "The next generation Androgen receptor (AR)-targeted therapies are now in widespread clinical use and prolong prostate cancer (CaP) patient survival." (PMID 31803623, 2019). "Our observation that AR antagonist induces telomere damage in AR-positive prostate cancer cells indicates a role of AR in telomere stability in these cells." (PMID 31083651, 2019). "The major signaling pathways implicated in prostate cancer such as PI3K, AKT, c-MYC, and AR give clues as to what is driving tumor growth and development." (PMID 31771198, 2019). "Selective targeting of PARP-2 by genetic or pharmacological approaches blocks the interaction between PARP-2 and FOXA1, attenuating AR-mediated gene expression and inhibiting AR-positive prostate cancer growth." (PMID 31366128, 2019). "Androgen ablation therapy is one of the therapeutic agents for prostate cancer which prevent androgen receptor (AR) function." (PMID 31801262, 2019). "A new molecule induces AR sumoylation and degradation resulting in selective growth inhibition in AR-dependent prostate cancer cells, but its activity is blunted by interference with proteasomes." (PMID 31431473, 2019). "During disease progression, genomic and epigenomic abnormalities accrued and converged on prostate cancer pathways, leading to a highly heterogeneous transcriptomic landscape, characterized by a hyperactive androgen receptor signaling axis." (PMID 31366128, 2019). "LAT3 protein expression is high in primary and recurrent prostate cancer, driven by direct androgen receptor (AR) transcription." (PMID 31345230, 2019). "In this study we report a novel molecular mechanism that explains how androgen steroid hormones control splicing patterns in prostate cancer cells, and unifies the functions of the AR both as a transcription factor and being able to control splicing." (PMID 31478829, 2019). "It is possible that the genes used to define the AR activity score are less relevant in ovarian cancer than they are in prostate cancer." (PMID 34926721, 2019). "The regulatory activity of the AR upon cellular survival makes its persistent activation a fundamental process at the basis of prostate cancer cells’ development and progression." (PMID 30642011, 2019). "We, therefore, examined the activation of mitochondrial apoptosis in response to AR antagonism in prostate cancer cell lines." (PMID 31228231, 2019). "According to these observations it concluded that AR reprograms prostate cancer cell metabolism, favoring extramitochondrial IDH1-mediated IDH activity." (PMID 31366128, 2019). "In SCID-NSG mice xenograft with human prostate cancer LNCaP/AR-Luc cells overexpressing the wild type androgen receptors (AR), decursinol (4.5 mg/mouse) decreases tumor growth and lung metastasis." (PMID 32116665, 2019). "Androgen deprivation therapy is able to control for some time hormone-naïve prostate cancers, but prostate cancer changes AR and adopt a series of adaptation mechanism to survive in the presence on only low levels of androgens as those induced by ADT." (PMID 31366128, 2019). "AR can also bind to the bromodomain of BRD4 to decrease the sensitivity of cancer cells to BET inhibitors in prostate cancer." (PMID 31718704, 2019). "Recently, dual targeting of HIF-1α and AR pathways by HIF-1α inhibitors and enzalutamide, a second generation AR inhibitor, showed synergistic effect in castration-resistant prostate cancer cell lines, also resulting in decreased VEGF-A levels." (PMID 31151317, 2019). "These behaviours are the hallmarks of castration-resistant prostate cancer underpinned by bypass signalling pathways characterised through various mechanisms of aberrant AR activation." (PMID 30742096, 2019).
prostate carcinoma (continued). "Previous work has suggested that the dependency of the prostate cancer cells on the FABP5-related pathway is increased gradually with a concomitant reduction in dependency on the AR-initiated pathway, until the former becomes completely dominant." (PMID 31258834, 2019). "A target gene of AR which is important for repression of prostate cancer progression is Snail Family Transcriptional Repressor 2 (SNAI2), yet its expression is repressed by enzalutamide-treatment induced GR expression." (PMID 31771198, 2019). "Taken together, these results demonstrate that BRCA2 levels modulate the sensitivity of prostate cancer cells to 6-TG to a similar extent as olaparib and that 6-TG treatment decreases the expression of AR independently on BRCA2." (PMID 31284411, 2019). "Androgen receptor (AR) is a member of the nuclear receptor superfamily and it has a central role in prostate cancer progression." (PMID 31261651, 2019). "Agonist-liganded human AR and antagonist-liganded AR bind to two distinct different motifs, leading to distinct transcriptional outcomes in prostate cancer cells." (PMID 31366128, 2019). "A recent report showed that transcriptionally active AR increases GLI transcriptional activity in prostate cancer cells." (PMID 31244888, 2019). "Downstream PI3K, P38 signaling inhibition modulates cell survival, migration, invasion, and NF-κB activation, known to contribute to prostate cancer progression and castration resistance through the regulation of AR activity." (PMID 31816863, 2019). "The abnormal activation of the androgen receptor (AR) is a major example of chromatin looping mechanisms that enhance gene expression in prostate cancer." (PMID 30634466, 2019). "Our results show that treatment of castration-resistant prostate cancer cells with 6-TG significantly decreased AR levels, independently on BRCA2 expression." (PMID 31284411, 2019). "Combination therapy cotargeting PI3K/Akt and AR signaling leads to significant regression of prostate cancer when compared with monotherapies, suggesting a coordinative role in supporting tumor survival." (PMID 31761786, 2019). "Together, our results provide novel insights into the regulation of the GR locus in the context of AR inhibition in prostate cancer cells, implicating TLE3 as a regulator of GR-mediated enzalutamide resistance." (PMID 31855178, 2019). "Androgen receptor (AR) is one of the nuclear receptors and the major therapeutic target in aggressive prostate cancer." (PMID 30987323, 2019). "Due to its central role in the cellular biology of prostate cancer (PC), androgen receptor (AR) still remains an important therapeutic target for fighting this tumor." (PMID 31192191, 2019). "In a genome-wide CRISPR-Cas9 screen using LNCaP prostate cancer cells, loss of co-repressor TLE3 conferred resistance to AR antagonists apalutamide and enzalutamide." (PMID 31855178, 2019). "AR is highly targeted in prostate cancer (PCa) at different stages of disease progression and namely earlier rather than late disease progression." (PMID 31771198, 2019). "Among these factors, GATA2 and FoxA1 play particularly essential roles in androgen receptor signaling in prostate cancer cells." (PMID 31552182, 2019). "We also find that the chromatin structure surrounding the androgen receptor (AR) locus is altered in the prostate cancer cells with many cancer-specific enhancer-promoter loops." (PMID 31515496, 2019). "EGCG was reported to physically interact with the ligand-binding domain of AR, which in turn decreased the transcriptional activity of AR and consequently reduced the growth of the prostate cancer cells." (PMID 30823649, 2019). "Our data, implicating TLE3 in the regulation of GR expression and drug resistance, complements increasing evidence describing the role of this receptor in bypassing AR blockade in prostate cancer cells." (PMID 31855178, 2019).